CD4 (CD4 molecule)
Diseases named in the same sentence as CD4 in open-access papers (continued):
Sharing a sentence is not in itself a finding about the gene and the disease.
infection (continued). "CD4+ T cell depletion increased the rate of congenital infection, viral loads in fetuses, and caused severe placental abnormalities in cases where the infected dams succumbed to infection before necropsy." (PMID 39495799, 2024). "Interestingly, people living with HIV with higher latest CD4 counts had a higher risk of infection, while those with higher HIV loads had a lower risk." (PMID 38630534, 2024). "In ART-treated PWH low CD4:CD8 ratios were associated with ADM and infection-related cancers independently from CD4 and CD8 cell counts and may alert clinicians for cancer screening and prevention of NADM." (PMID 38092042, 2024). "Conversely to the promise of IL-15 as an LRA, the pro-survival effects have been implicated in sustaining persistent HIV infection by enhancing susceptibility of CD4+ T cells to infection in a SAMHD1-dependent manner, as well as promoting proliferation of CD4+CCR5+ T cells." (PMID 39401241, 2024). "All gorilla CD4 variants were equal to, or more resistant to infection than, the human CD4." (PMID 38014262, 2024). "An earlier study conducted in patients with (hematologic) malignancies infected with SARS-CoV-2 wild-type demonstrated that the presence of SARS-CoV-2–specific CD4+ T cells in the weeks after infection is associated with a reduced time to viral clearance, using a similar cut-off of 30 days." (PMID 38843052, 2024). "In addition, NMI infection elicited a comparable level of protection in Wild type, CD4+ T cell deficient, and CD8+ T cell deficient mice, partial protection in B cell deficient mice but no protection in T cell deficient mice." (PMID 39469719, 2024). "In parallel, these Fas/FasL-deficient mice showed a severely impaired infection-induced CNS inflammatory response with lower levels of infiltrating CD4+ T-cells, lower levels of Th1 cytokines and chemokines, and a shift in the balance between M1 and M2 microglia/monocytes." (PMID 39339840, 2024). "Suggestions for potential areas of study could come in the form of a retrospective analysis of infection risk in patients with CVID with varying CD4/CD8 ratios as well as analyzing for any potential mortality effects related to CD4/CD8 ratios." (PMID 39728019, 2024). "As suggested by the authors, this may be due to IL-15-induced CD4+ T cell activation, which increased their susceptibility to infection." (PMID 39459922, 2024). "For this reason, it is believed that the virus infects CD4+ T cells in a short timeframe, where a small pool of activated T cells differentiates into long-term memory T cells when they are still susceptible to infection." (PMID 38400005, 2024). "Immune cell population density and locations changed dramatically over the course of infection, wherein red pulp expansion was the result of increases in CD3, CD4, CD8 and NK/NKT cells, while white pulp contraction with infection was largely the result of CD4 cell loss." (PMID 38408129, 2024). "Where multiple variants initiate infection, recipient set point viral load (SpVL) and the rate of CD4+ T cell decline may be elevated, but these findings remain inconsistent." (PMID 39471873, 2024). "To compare our model framework with the outcome variables used in observational studies, we calculated the mean SpVLs for single and multiple variant infection as well as the proportion of each risk group that would have an excess of 350 CD4+ T cells mm−3 over time." (PMID 39471873, 2024). "This may suggest that it is not an inherent virological property of the founder viruses that drives an association with a faster rate of CD4+ T cell decline, but instead how the presence of multiple variants determines disease dynamics in early infection." (PMID 39471873, 2024). "Interestingly, a recent finding reported that the Vpu membrane-associated HIV-1 auxiliary protein, which facilitates viral dissemination, can enhance the susceptibility of macrophages to infection through the phagocytosis of infected CD4+ T cells." (PMID 38400063, 2024).
infection (continued). "To establish whether available data can explain the probability that infection is initiated by multiple variants, SpVL and the rate of CD4+ T cell decline, we designed a model framework characterising HIV-1 transmission and disease progression." (PMID 39471873, 2024). "Thus, L. major-infected CXCR3-/- mice are more susceptible to infection due to a reduced number of CD4+T cells producing IFNγ in the lesion." (PMID 38709823, 2024). "To identify which components are responsible for the primary NMI-infection induced protection, we examined if B cell, T cell, CD4+ T cell or CD8+ T cell deficiency in mice will significantly affect primary NMI-infection induced protective immunity against NMI reinfection." (PMID 39469719, 2024). "Across all risk groups, the median time to a clinically significant recipient CD4+ T cell count associated with single variant infection was significantly less dispersed than those from infections initiated by multiple variants (paired, single-tailed t‐test, p = 0.003)." (PMID 39471873, 2024). "Furthermore, the identification of low CD4 values (<200 cells/μL) as an added risk factor suggests a greater susceptibility to infection and as previously reported, heightened inflammation and tissue damage." (PMID 38251391, 2024). "Data not only confirm previous findings of Leishmania infection with PBD leukocytes and association with B cells but also suggest that CD4+ T cells might influence the early-stage of infection." (PMID 39338584, 2024). "In addition, CD39+ DN T-cells were positively associated with both the duration of infection and treatment and negatively correlated with the CD4/CD8 ratio, which aligns with previous reports connecting CD39 expression and HIV disease progression." (PMID 39459942, 2024). "T cell lymphopenia has been widely reported during the acute phase of COVID-19 infection and a small study investigating the T cell profile in a cohort of 13 convalescent patients, four weeks post-resolution of infection observed a loss of naïve CD4 T cells and accumulation of memory T cells." (PMID 38212801, 2024). "This analysis revealed women infected with multiple variant infections would reach a CD4+ T cell count of less than 350 cells mm−3 in 39.2 months (95% confidence interval (CI): 30.8–47.6), significantly faster than 56.8 months (46.0–67.7) for those with single variant infections." (PMID 39471873, 2024). "Indeed, our results showed that NF1_LV infection resulted in increased expression of markers genes (namely Cd4) encoding for lymphocytes (T and B cells)." (PMID 39735262, 2024). "Taken together, these data show that mucosal immunity following a single S. pyogenes IN infection is associated with an increase in M1-specific IgG and IgA antibodies in the saliva, alongside the expansion of neutrophils, effector/memory CD4+ T cells, and IL-17+ cells in the lung." (PMID 38576622, 2024). "Unexpectedly, the CD4+ T cell expression of two known correlates of HIV infection susceptibly, CCR5 and integrin-α4β7, increased following menopause across all three tissues despite only being associated with increased infection frequency in EM derived CD4+ T cells." (PMID 39872519, 2024). "Moreover, CD4+ T cells from the case were equally susceptible to infection with the laboratory strain NL4-3 BaL compared with CD4+ T cells from HIV-negative donors." (PMID 37702421, 2023). "The lower CCR5 expression on CD4+ T cells of MCMs may contribute to reduced susceptibility to infection and may help explain the differential reservoir sizes between RMs and MCMs." (PMID 37747933, 2023). "In addition to consciousness disorder increasing the patient's risk of infection, the risk for early infection increases when CD4+ T-cell levels in the blood are <300/μL." (PMID 37360336, 2023).
infection (continued). "However, infusion of IgG purified from seropositive RMs with robust anti-RhCMV neutralizing responses prior to infection leads to a reduction in maternal plasma VL and demonstrated protection in this extremely high risk setting of CD4-depletion." (PMID 37871009, 2023). "Depending on whether CD4-⍺4β7 interactions enhance or inhibit infection, it follows that circumstances that promote this interaction define a condition in which CD4+ T cells are either more or less susceptible to productive infection." (PMID 38064524, 2023). "Thus, breakthrough infection caused an obvious decrease in CD4 counts in heterologous booster individuals and a decrease in CD8 counts for the homologous booster group in PLWH." (PMID 38140668, 2023). "For example, a decrease in CD4 expression may indicate a decrease in T helper cell function, which can impair the immune response and increase susceptibility to infections." (PMID 37465154, 2023). "Notably, the risk of Bh infection significantly decreased within the CD4+ T cell rose from 0 cells/μl to 500 cells/μl." (PMID 37697423, 2023). "Our analysis showed a positive association between CD4 + T cell immune staining at the infection site, bacterial load, the number of lesions (as shown in Table-1), and the number of affected cells in M.tb-infected guinea pigs after the 4th week of post-infection." (PMID 38036985, 2023). "We also observed a significant reduction in both the level of Bcl-6 protein expression and frequency of NP-specific Bcl-6+ cells in Aiolos-deficient CD4+ T cells at an early timepoint post-infection, supporting a role for Aiolos in the positive regulation of Bcl6 expression in vivo." (PMID 36964178, 2023). "We thus hypothesize that the dCA-resistant HIV-1 variants selected in vitro in HeLa-CD4 cells lose fitness in vivo and that the few animals in which a delayed infection was observed, did so by reverting to the WT virus." (PMID 37112931, 2023). "Collectively, results of the IL-10R blockade study showed that IL-10 plays a role in attenuating the level of lung inflammation, as well as in decreasing CD4+ T cell proliferation and the Th1 response in B cell-deficient mice during the chronic phase of infection." (PMID 36888692, 2023). "Moreover, recent studies by our group and others have shown that CD4+ T cells are involved in controlling the parasite burden and that CD4+ T-cell deficiency promotes the development and growth of hydatid cysts during infection." (PMID 37930989, 2023). "Details of these CD4+ T cell responses would allow insight into both epitope selection and immunodominance and the mechanism(s) behind loss of T cell responses that independently associate with recurrent infection." (PMID 37471227, 2023). "Furthermore, viral vector vaccines, lower CD4 T cell count/viremia and old age have been linked to lower serological responses and breakthrough infection." (PMID 36590902, 2023). "We speculate that the reduced CD3 + CD4 + T cell count increases the risk of infection and thus contributes to the occurrence of AE." (PMID 37773193, 2023). "TAR transferred by EVs appears to render naïve CD4 T lymphocytes more susceptible to infection." (PMID 36766808, 2023). "HTLV-1 infects CD4+ T-cells and causes a persistent life-long infection of the host." (PMID 36819050, 2023). "Hence, the purpose of the study was to explore the association between Bh infection risk and CD4+ T cell counts, HIV viral load (VL), and duration of interruption in antiviral therapy among PLWH." (PMID 37697423, 2023). "However, they also observed that the mutated epitopes were poorly recognized by CD4 T cells developed after infection with the Beta variant." (PMID 36752852, 2023). "PWH with a CD4+ T-cell count <350 cells/μL may have a compromised immune system and are more susceptible to inflammation and infection, which may contribute to the development of physical frailty." (PMID 38033984, 2023).
infection (continued). "CD4+ tissue resident memory T cells (TRMs) are implicated in the formation of persistent HIV reservoirs that are established during the very early stages of infection." (PMID 36897929, 2023). "While R5 variants are known to dominate early infection, a switch to X4 at later stage of infection occurs in roughly 50% of patients infected with subtype B HIV-1 associated with increased depletion of CD4+ T cells, faster progression to AIDS, and a higher mortality rate." (PMID 38127856, 2023). "It has also been reported that infection of rhesus monkeys with host-range mutant human adenovirus type 5 suppressed their innate immune response and induced systemic CD4+ T cell activation, suggesting that mutations in adenovirus have the potential to affect the immune response of the host." (PMID 37035797, 2023). "In the short-term follow-up, six months after recovery, all patients showed high SARS-CoV-2-specific T-cells response, suggesting its possible association with the prior episode of severe infection, and the magnitude response was found in TemRA CD4 T-cell and EM CD8 T-cell memory subsets." (PMID 37240647, 2023). "Additionally, as the number of covariates increased, the presence of other important variables influenced the risk of Bh infection in conjunction with CD4+ T cell counts within the range of 0 to 500 cells/μl." (PMID 37697423, 2023). "The CD4+ T cell decline estimates differ by the viral subtype causing the infection." (PMID 37161335, 2023). "Since, in our findings, a strong down-regulation of CD4 in koi carp could be speculated to be caused by the elevated viral transcripts infected with genogroup I or IIa post-infection." (PMID 37465154, 2023). "The humoral and CD4+ T cell response induced by natural infection and/or vaccination with the Wuhan variant can cross-recognize several viral variants of interest and concern that circulated in Colombia during the second and third waves that occurred in the country." (PMID 37575243, 2023). "In addition, a study reported that IL-17 positively regulates CD4+ T cells to facilitate the immune system against pathogenic infection." (PMID 36911690, 2023). "Furthermore, the development of bNAbs is associated with the duration of infection, plasma viraemia, viral diversity, CD4+ T cell decline and the Fc effector functions." (PMID 37267224, 2023). "Similarly, pre-existing cross-reactive T cells facilitated the expansion of SARS-CoV-2-specific CD8+ and CD4+ T cell responses during infection and were associated with control of viral replication and abortive infection." (PMID 36776863, 2023). "In cART-treated patients, levels of pro-inflammatory cytokines are also associated with increased risk of CVD, independently from other CVD risk factors, and with infection-related and unrelated cancers, even after adjusting for demographics and CD4+ T cell counts." (PMID 36672667, 2023). "Furthermore, other infection models have shown that loss of Bhlhe40, specifically in CD4+ T cells, results in pronounced disease." (PMID 37843306, 2023). "People with a CD4+ T cell count < 200 cells/μL are at risk for this infection." (PMID 37887742, 2023). "In addition, B cell MHCII expression enhances susceptibility to infection in a CD4+ T cell-dependent manner, and we found that follicular B cells are sufficient to inhibit CD4+ T cell-mediated immunity against Brucella." (PMID 37721965, 2023). "During acute infection, infiltration of CD4 cells and monocytes from the blood to the brain allows for infection of the microglia and perivascular macrophages, causing neurological disorders, such as asymptomatic neurocognitive impairment, mild neurocognitive disorder, and HIV-associated dementia." (PMID 35062339, 2022). "The demonstration that Spike-specific CD4+ T cells from subjects with previous Alpha variant infection recognize also the ancestral protein, suggests that vaccination may rapidly reactivate immunological memory to Spike protein also in these individuals." (PMID 35154116, 2022).
infection (continued). "Early in HIV infection, increased IFNα levels are considered to restrict infection, i.e., they are beneficial, whereas elevated levels later in disease are associated with disease progression, with increased viral loads and decreased CD4+ T cell counts." (PMID 36032117, 2022). "The authors discovered that the existence of preexisting CD3+CD4+CD161+ cells might play a significant role in reducing the risk of severe infection in patients with RRMM after Rd treatment." (PMID 36233774, 2022). "Similarly, from 127 discordant couples, higher viral replication capacity (vRC) early in infection was associated with faster decline of CD4 T cell counts." (PMID 35271687, 2022). "Therefore, although we found a similar association with infection risk for CD4 and CD8 T cell response, it should be interpreted as the protective effects were mainly from the CD4 T cell response." (PMID 35858844, 2022). "Moreover, despite a mild difference for Alpha variant, we observed substantially comparable responses to reference and mutated pools, suggesting that CD4+ T cells induced by ancestral infection or vaccination cross-react to Alpha, Beta and Delta variants." (PMID 35154116, 2022). "To rule out that the vaccine had caused nonspecific immune activation that could promote increased susceptibility to infection, we tested for activation of peripheral blood CD4+ T cells, the main target cells for HIV." (PMID 35196125, 2022). "Moreover, we were also interested in assessing the polarization of phenotypic responses of CD4+Th cells following infection, and its potential association with the severity of infection." (PMID 36578502, 2022). "Furthermore, mice deficient in T-bet expression or with a CD4-specific T-bet deficiency cleared FRT infection similarly to wild-type controls." (PMID 35196366, 2022). "infection includes humoral and cell-mediated mechanisms that may be disrupted by a feline retrovirus, thereby underlining the lowest CD4+/CD8+ ratio in our study." (PMID 36425135, 2022). "Additionally, the cohort selected for this study was composed by immunodiscordant individuals, whose low CD4+ counts after viral suppression made them prone to infections that required antibiotic treatment, causing many dropouts." (PMID 36569851, 2022). "Furthermore, we used CD4 T-cell deficient mice to specifically investigate the role of CD4+ T cells in the modulation of the course of E. granulosus s.s. infection." (PMID 36046744, 2022). "CD4 loss was calculated based on absolute counts of CD101+ CD4 pre- and post-infection." (PMID 35867722, 2022). "Furthermore, viral vector vaccines, lower CD4 T cell count/viraemia and old age have been linked to lower serological responses and breakthrough infection." (PMID 36380764, 2022). "We show that the CeD-associated CD4+ T cells are transcriptionally associated with several infection-related pathways, which could be a result of intestinal microbiome alterations in CeD patients." (PMID 35995787, 2022). "We and others have shown before that the TCRβ repertoire of CD4 T cells encodes the antigen exposure history of each individual and that antigen-specific TCRβ sequences could serve to automatically annotate the infection or exposure history." (PMID 35074048, 2022). "Indeed, we show that infection of MΦ through cell-to-cell virus transfer is linked to enhanced Env interactions with CD4 and the coreceptor, thereby making viral entry less dependent on the expression level of both receptors at the surface of MΦ." (PMID 35622876, 2022). "For comparison, previous studies have demonstrated that oral infection with A. ceylanicum is associated with a reduction in CD4+ splenocytes and CD4+ MLNs, as well as reduced numbers of IgG+ B cells in the spleen, compared to uninfected controls at day 20 post-infection." (PMID 34986139, 2022).